IL1A (interleukin 1 alpha)
Diseases named in the same sentence as IL1A in open-access papers (continued):
Sharing a sentence is not in itself a finding about the gene and the disease.
COVID-19 (continued). "Actually, IL-1α has recently been described as an early marker to predict a bad outcome in COVID-19 severe patients." (PMID 36238287, 2022). "Initial COVID-19 studies revealed higher levels of IL-1α, which is a cytokine of initial states of the innate immune response." (PMID 36238287, 2022). "Higher levels of IL-1α and IL-18 pro-inflammatory cytokines were also found in fatal COVID-19 serum." (PMID 35386707, 2022). "There was a significant increase in the concentration of 40 cytokines/chemokines in a conditioned medium, including TNF-α, IFN-α, IL-6, and IL-1a, which corresponded to the cytokine profile in patients with severe manifestation of COVID-19." (PMID 36290634, 2022). "Here, the lower expression of DUSP1 observed in SARS-CoV-2 infected cells and nasopharyngeal swabs of severe COVID-19 patients was associated with the higher expression of TNF-α, IL-1β, and IL-1A genes (respectively)." (PMID 33995033, 2021). "These thrombi cleaved IL-1α were found to be elevated among COVID-19 patients, exhibiting severe lung injury." (PMID 34372552, 2021). "Biomarkers associated with endothelial integrity and sepsis severity are increased in COVID-19, while plasma gelsolin and IL-1α levels are decreased in patients who die from COVID-19." (PMID 33232303, 2021). "PIMS-TS children had significantly elevated levels of cytokines, IFNγ, IL-2, TNFα, IL-1α, IFNα, IFNβ, IL-6, IL-17A, GM-CSF, IL-10, IL-33 and IL-Ra in comparison to COVID-19, seropositive and control children." (PMID 33813138, 2021). "Our present results identified obvious elevations of various cytokines in patients with severe COVID-19, including IL-1α, IL-1β, IFN-γ, TNF-α, IL-2, IL-4, IL-6, IL-10, and IL-17A." (PMID 34113636, 2021). "The SAVE-MORE phase 3 study demonstrates the efficacy of anakinra, an IL-1α/β inhibitor, in patients with COVID-19 and high serum levels of soluble plasminogen activator receptor." (PMID 34480127, 2021). "CRP was positively associated with IFNγ, IL-2, TNFα IL-1α IFNβ IL-6 IL-17A IL-10, CXCL-10 and VEGF in children with PIMS-TS and COVID-19." (PMID 33813138, 2021). "Lymphocyte count was negatively associated with IFNγ, IL-2, TNFα, IL-1α, IFNβ, IL-6, IL-17A, IL-10, CXCL-10 and VEGF in children with PIMS-TS and COVID-19." (PMID 33813138, 2021). "Recently research indicated that suspected sHLH related to COVID-19 received IL-6 antagonistic therapy and Anakinra (recombinant soluble receptor antagonist of IL-1β and IL-1α)." (PMID 33926377, 2021). "COVID-19 children had elevated levels of IFNγ, IL-2, TNFα, IL-1α, IFNα, IFNβ, IL-6, IL-17A and IL-10 in comparison to seropositive and/or control children." (PMID 33813138, 2021). "Other highly-ranked genes included proposed prognostic factors (CXCL10, CD4, CD3E) and investigational therapeutic targets (IL1A) for COVID-19." (PMID 33339864, 2020). "The activated mechanistic networks in patients with severe COVID-19 highlighted the predicted relationship between IL1A, IL1B, and TNF, and their regulation in gene datasets based on Z scores." (PMID 33138195, 2020). "The results revealed that polymorphisms in the IL6, IL6R, IL1α, IL1R, IFNγ, TNFα, CRP, VDR, VDBP, and ACE2 genes are the most significant genetic factors influencing COVID-19 prognosis, particularly in terms of the risks of COVID-19 pneumonia, mortality, rehospitalization, and associated mortality." (PMID 40869297, 2025). "IL1A is expressed in lung cells, and it predicts a bad prognosis for COVID-19." (PMID 38543303, 2024). "IL-1α was found to show a slight elevation in its levels in moderate and severe COVID-19 patients." (PMID 38855114, 2024). "Treatment of these mice with anakinra (which blocks both IL-1α and IL-1β signaling) or with antibodies selectively targeting IL-1α significantly attenuated COVID-19-like pulmonary immunopathology, potentially identifying IL-1α as a mediator of inflammation and tissue-specific injury." (PMID 39882243, 2024).
COVID-19 (continued). "Together, these findings highlight the essential role of macrophages as the major inflammasome-activating cell population in the lungs and point to endothelial cell expressed IL-1α as a potential novel component driving the pulmonary immunothromobosis in COVID-19." (PMID 38664396, 2024). "In this study, we screened for c-aAb targeting IFNα, IFNβ, IFNγ, IL-1α, IL-6, IL-10, and GM-CSF in the Surviving Pneumonia Study cohort, comprising 665 patients with CAP caused by COVID-19, influenza virus, bacteria, or unknown pathogen." (PMID 39606243, 2024). "However, in this study, an upregulation of other pro-inflammatory cytokines, including CRNN, IL1A, IL23A, IVL, and S100A7, was associated with severe COVID-19." (PMID 38375062, 2024). "In COVID-19, IL-1α is massively released by lung epithelium cells, activating alveolar macrophages." (PMID 37834869, 2023). "It seems IL-1α is studied less frequently in COVID-19 than IL-1β." (PMID 37928695, 2023). "Particularly, an increased susceptibility for Candida infections in critically ill COVID-19 patients was suggested by the observation of impaired immune response to those pathogens characterized by the abrogated release of IL-6, TNF, IL-1α, and IL-1β toward Candida albicans." (PMID 36675940, 2023). "Based on this evidence, the efficacy of IL-1 blockade may be related to endotheliopathy of COVID-19 to secrete IL-1α." (PMID 35619180, 2022). "In addition, we analyzed the possible binding between VD3 and the top 5 STAD/COVID-19 core target proteins (IL1A, IL8, ALBU, CSF2, PAI1) identified in the STRING analysis." (PMID 35571107, 2022). "Our clinical obeservation indicated that the patient B showed low level of cytokines such as IL-6, MCP-3, MCP-1, IP-10 and IL-1α after treatment with LS, which hinted that LS could prevent COVID-19 into hyperinflammatory status." (PMID 35365215, 2022). "Individual genes associated with the COVID-19/sepsis shared hypermethylated and hypomethylated CpG genes include type I IFN-related genes, like IRF2, and others, such as IL1A and CCR2, that are involved in inflammatory processes and monocyte chemotaxis, respectively." (PMID 36443794, 2022). "According to several clinical studies, specific blockade of IL-1α with monoclonal antibodies may have beneficial effects in alleviating the inflammatory storm in severe COVID-19 cases." (PMID 35619180, 2022). "Based on this, the increase in inflammatory cytokines in COVID-19, including IL-1α expressed in platelets, monocytes, and endothelial cells under proinflammatory conditions, constitutes a link between the inflammatory response and activation of the coagulation system." (PMID 36292285, 2022). "A transcriptomic study of COVID-19 patients showed the induction of IL1A in nasopharyngeal samples." (PMID 34931923, 2021). "In severe cases of COVID-19 patients, increased IL-1α and IL-1β have been detected." (PMID 34054828, 2021). "We have found fifteen cytokines that remain upregulated in convalescent COVID-19 individuals one month after infection (IL-1α, IL-3, IL-10, IL-12p70, CCL7, IFN-α2, bFGF, LIF, TRAIL, IL-2, IL-4, IL-5, IL-12p40, IL-17 and MIF) indicating a strong activation of the immune response." (PMID 34681885, 2021). "Whilst, ILR1α, IL-1α and IL-18 levels were reduced in Asymptomatic COVID-19." (PMID 34824360, 2021). "Notably, IL-1α induces IL-6 expression, which has emerged as a promising target for COVID-19 treatment." (PMID 33003552, 2020). "Although mechanistic insight into the host inflammatory response to COVID-19 is still limited, it is likely that both IL-1α and IL-1β play a central role in the development of the exuberant, maladaptive inflammatory response leading to life-threatening states in some patients." (PMID 33442386, 2020). "Together, with epithelial cells, IL-1α expressing endothelium could explain positive outcome of anakinra (IL-1 receptor antagonist) in a subgroup of COVID-19 patients, and specifically IL-1α blockade in animal model of COVID-19." (PMID 38664396, 2024).
COVID-19 (continued). "However, in COVID-19 patients, it was negatively correlated with IL-1α and IL-33." (PMID 38855114, 2024). "An example of such a marker might be the soluble urokinase plasminogen activator receptor (suPAR) that predicts the progression to respiratory failure in COVID-19 patients and, targeting this pathway, the IL-1α/β inhibitor anakinra is now undergoing clinical trials." (PMID 36451808, 2022). "TGF-β might also participate in the mechanisms of ECM remodeling underlying post-COVID-19 sequelae, as it was revealed by Colarusso and others (2021) who found higher TGF-β, CXCL10, and IL-1α plasma levels in post-COVID-19 patients who exhibited ground-glass opacities in the chest CT scan." (PMID 35647937, 2022). "In this study, the levels of TNF-α, IL-1α, IL-4, IL-6, IL-8, and IL-10, were measured through ELISA in sera from healthy volunteers as a control group, patients with moderate COVID-19, patients with severe COVID-19, and patients who had recovered from COVID-19." (PMID 33914789, 2021). "Our findings highlight IL-1α and ADAMTS13 autoantibodies as independent predictors of mortality in severe COVID-19, reflecting the interplay between inflammatory and endothelial pathways." (PMID 41683699, 2026). "As expected, plasma concentrations of several inflammatory mediators, including IL-1α, IL-6, IL-18, IP-10, HGF, MCP-3, and M-CSF, were elevated in patients with acute COVID-19, especially those with severe disease." (PMID 39847442, 2025). "More evidence links COVID-19 to cytokine release syndrome, specifically elevated pro-inflammatory cytokines (IL-1β, IL-6, TNF-α, and IL-1α) in extreme cases." (PMID 41293155, 2025). "Genes within this pathway, including IL1A and TNF, were more expressed in moderate and severe COVID-19 cases compared to RSV." (PMID 39877087, 2025). "In fact, when compared to controls, amniotic fluid from COVID-19-affected pregnancies demonstrated elevated levels of several pro-inflammatory cytokines, including IL-12 p40, CCL4, CCL7, CCL13, TNF, IL-1a, IL-17A, and IL-17E." (PMID 39390219, 2024). "Importantly, both single viroporins and SARS-CoV-2 virus could induce IL-1α and IL-33 expression and release not only in pulmonary epithelial cell but also microvascular endothelium shedding novel light on the inflammatory response of endothelium in COVID-19." (PMID 38664396, 2024). "Cytokines, such as IL1A and IL27, which have been shown to be higher in patients with more severe COVID-19 disease, were highly expressed in COVID-19(+) TV skin in comparison to the other groups." (PMID 37026002, 2023). "First, we measured plasma levels of 8 cytokines (IFN-α, IL-1α, IL-1β, IL-10, IL-6, IL-8, S100A8/A9 (calprotectin), and TNF-α), which were shown to be upregulated in the blood of severe COVID-19 patients." (PMID 38082066, 2023). "Anakinra is an antagonist of IL‐1 receptor, which inhibits IL‐1α and IL‐1β activities, and is approved by the FDA to be used to treat adult COVID-19 inpatients with positiveness of COVID-19 with pneumonia and requiring supplemental oxygen." (PMID 37726282, 2023). "Reelin level was highly correlated with IL-1α, IL-4, IP-10, MIP-1β, and ICAM-1, suggesting a specific role for Reelin in COVID-19 progression." (PMID 37441066, 2023). "IL-1α, IL-1β, IL-8, IFN-γ, VEGF-A, and TNF-α had returned to normal levels 6 months after recovery, but IL-1Rα was still elevated in COVID-19 convalescents, compared to healthy controls." (PMID 37077911, 2023). "Reelin level was correlated with IL-1α, IL-4, IP-10, MIP-1β, and ICAM-1, suggesting a specific role for Reelin in COVID-19 progression." (PMID 37441066, 2023). "In the current study, we performed direct comparisons of cytokine expressions in KD and severe COVID and found that the expressions of IL1A, IL1R1, and TNF were about 2.6- to 10-fold higher in severe COVID-19 than in KD." (PMID 36159873, 2022).
COVID-19 (continued). "In male participants, EGF, GM-CSF, IL-1ra, IL-1α, IL-1β, IL-2, IL-4, IL-7, IL-15, EOTAXIN, MDC, MIP-1α, MIP-1β, IFNα2, and sCD40L were significantly lower in COVID-19 patients compared to controls." (PMID 36554094, 2022). "Seven out of the 16 known cytokine markers (including IL1A, IL1R1, CCL2, IL6, IL10, CXCL10, and VEGFA) were less pronounced in KD than in severe COVID-19 patients compared to FC and HC, respectively." (PMID 36159873, 2022). "Serum levels of EGF, G-CSF, GM-CSF, IL-1ra, IL-1α, IL-1β, IL-2, IL-4, IL-7, IL-8, EOTAXIN, fractalkine, GRO, P-10, MDC, MIP-1α, MIP-1β, IFNα2, and sCD40L were significantly lower in female COVID-19 patients compared to controls." (PMID 36554094, 2022). "A variety of cytokines and chemokines including IL-1α, IL-6, IP-10, MCP-1, MIP-1α and IFN-γ had been found to be significantly elevated in the serum of COVID-19 patients." (PMID 35365215, 2022). "We also measured the epithelial cell–derived biomarkers S100A8, regenerating islet-derived protein 3 alpha (REG3A), and IL-1α and found both S100A8 and REG3A levels to be modestly increased in COVID-19 patients relative to HVs across all severity categories." (PMID 33232303, 2021). "In severe COVID-19, a similar pattern was observed but weakly lower on SCGF and MPO and weakly higher on IL-1α and IL-17." (PMID 34238349, 2021). "In our analysis, we identified two target gene clusters of biochanin A including inflammatory genes (IL1A, IL2, and IL6R) and cell proliferation genes (CCND1, PPARG, and EGFR) relevant to the treatment of CRC/COVID-19." (PMID 34931923, 2021). "It has been shown that capillary leak, the major factor deteriorating lung function in patients with COVID-19, is driven by TNF-α, IL-1A, and IL-6 inflammatory cytokines." (PMID 33995033, 2021). "A set of cytokines were upregulated in SputnikV immunized individuals (IL-1α, IL-3, IL-10, IL-12p70, CCL7, IFN-α2, bFGF, LIF and TRAIL), where nine of them were similar to that in convalescent COVID-19." (PMID 34681885, 2021). "We have identified gene clusters associated with CRC, COVID-19, and biochanin A. Bioinformatic analysis further showed the involvement of six core targets of biochanin A in the treatment of CRC/COVID-19, including EGFR, CCND1, IL2, IL1A, IL6R, and PPARG." (PMID 34931923, 2021). "Using the network pharmacology approach, we identified two clusters of genes involved in immune response (IL1A, IL2, and IL6R) and cell proliferation (CCND1, PPARG, and EGFR) mediated by biochanin A in CRC/COVID-19 condition." (PMID 34931923, 2021). "The hyperinflammatory response in COVID-19 is characterized by elevated levels of serum TNF-α, IL-6, and to a lower level IL-1A since this cytokine has a short serum half-life." (PMID 33995033, 2021). "The level of these cytokines was also elevated in nasopharyngeal swabs of severe COVID-19 patients compared to healthy controls (for TNF-α, IL-1β and IL-1A, for IL-6, IL-8 and IL-23)." (PMID 33995033, 2021). "Increased pro-inflammatory cytokines and neutrophils infiltration were present in severe COVID-19 patients, in our murine ARDS model, we noticed the increased pro-inflammatory cytokines IL-6, TNF-α, and IL-1α in BALF." (PMID 33584719, 2020). "In our study, we found that the interleukins primarily involved in TEN were IL-4, IL-6, and IL-12, which were modulated (downregulated) by TEN, along with augmented IL-1α, IL-1β, IL-5, IL-8, NF-κβ, and interferons (IFN; α, β, and γ), which were modulated by COVID-19." (PMID 39941142, 2025). "Notably, convalescent serum showed significant decreases in sICAM-1, sVCAM-1, P-selectin, IL-1α, IL-1ra, IL-10, IL-27, TNF-α, TGF-α, and G-CSF compared to serum from severe COVID-19 patients." (PMID 41583455, 2025).
COVID-19 (continued). "Select genes that were highly expressed in COVID-19(+) TV specimens compared to COVID-19(+) PU and COVID-19(-) PU control groups play a central role in regulation of innate immune responses and defense to viral infection, including CARD8, IL1A, CD274, TRIM35, IRF7, and IFIH1." (PMID 37026002, 2023). "Acute COVID-19 children had significantly elevated levels of cytokines, (Interferon (IFN)) IFNγ, Interleukins (IL)-2, TNFα, IL-1α, IL-1β, IFNα, IFNβ, IL-6, IL-12, IL-17A and Granulocyte-Colony Stimulating Factors (G-CSF) in comparison to convalescent COVID-19 and controls." (PMID 37013538, 2023). "In support of this hypothesis, a recent study found that COVID-19 patients had reduced upregulation of CD80 on monocytes and abrogated release of IL-6, TNF, IL-1a and IL-1b in response to Candida albicans." (PMID 38169876, 2023). "We observed increased serum levels of IL-1α prior to a rise in IL-6 levels in the sera of severely affected COVID-19 patients, independent of ECMO therapy." (PMID 37834869, 2023). "As expected, significantly increased activation of pro-inflammatory cytokines (IL-1α, IL-2Ra, IL-6, IL-8, and IL-18) in fatal COVID-19 compared to non-fatal COVID-19 sera was measured." (PMID 35386707, 2022). "Several mediators such as Tie-2, VEGFA, IL-17D, IL-3, GM-CSF, IL-1α, IL-5, Eotaxin 3, IL-12p70 and IL-13 were not significantly different between COVID-19 and control subjects (data not shown)." (PMID 36116160, 2022). "Our data show that the levels of these IL-1α, IL-1β IL-6 and IL-18 cytokines are significantly lower in severe COVID-19 survivors than in non-survivors." (PMID 36142255, 2022). "In post-COVID-19 patients, we observed co-upregulation of groups of related red module proteins such as the CXCR3 chemokines (CXCL9, CXCL10, and CXCL11), and interleukin-1A (IL1A) and its antagonist IL1RN." (PMID 35151371, 2022). "The only expression of IL-1α, IL-1β, IL1 receptor and their signaling pathway molecules had been induced before the lowest respiratory system function (up to 3-5 days after the onset of COVID-19 symptoms) in patients with poor outcomes." (PMID 35126355, 2021). "Furthermore, blood levels of IL1α, calprotectin (a heterodimer made of S100A8 and S100A9), S100A12, S100B and HGBM1 appear to correlate with COVID-19 severity." (PMID 34293006, 2021). "Therefore, the early detection of HGF, IL-1α, and IL27 plasma levels in patients in COVID-19 patients can provide useful information for getting quickly intensive treatment as well as providing possible therapeutic targets." (PMID 34066892, 2021). "Based on our previous studies, we found that higher levels of IL-1α and TGF-β, but lower levels of IFN-β, could reflect the increased RR (3-fold; RR = 2.8) of lung fibrosis-like changes in both severe and moderate COVID-19-affected patients post infection." (PMID 34944747, 2021). "Our results showed 13 potential targets of biochanin A; the molecular interaction network analysis using Cytoscape further highlighted the involvement of six core targets of biochanin A, EGFR, CCND1, IL2, IL1A, IL6R, and PPARG, for the treatment of CRC/COVID-19." (PMID 34931923, 2021). "In this regard, we hereby report that HGF, IL1α, and IL27 contribute to the deterioration of the disease and the adverse outcome of COVID-19 revealing these three compounds as novel biomarkers but as future therapeutic targets in COVID-19." (PMID 34066892, 2021). "No appreciable changes were observed in IL-12p40, IL-18, or IL-1A in COVID-19-(+) plasma samples versus controls." (PMID 33245731, 2020). "The expression levels of a 13-cytokine panel (IL-1α, IL-1β, IL-2, IL-4, IL-5, IL-6, IL-8, IL-10, IL-12, NF-κβ, and IFN-α, IFN-β, and IFN-γ) were measured by qRT-PCR from peripheral blood mononuclear cells (PBMC) obtained from the patient with TEN and their parents (which were positive for COVID-19)." (PMID 39941142, 2025).